IL6 (interleukin 6)
Diseases named in the same sentence as IL6 in open-access papers (continued):
Sharing a sentence is not in itself a finding about the gene and the disease.
breast cancer (continued). "Apart from this, STAT3 inhibition can regulate the production of various immunomodulator factors in TME of breast cancer, such as upregulation of INFs, GM-CSF and IL-2, downregulation of TGF-b, IL-6, and IL-10 proteins." (PMID 33957948, 2021). "In late stage breast cancer tissues, transient expression of miR-181b is activated by STAT3, a transcription factor activated by IL-6, which results eventually in upregulation of NF-kB and downregulation of let-7a." (PMID 33901254, 2021). "The expression of inflammatory cytokines, such as interleukin-6 (IL6) and Tumor necrosis factor alpha (TNFα), have been related to an increase in invasiveness and a poor prognosis in breast cancer." (PMID 34573003, 2021). "In breast cancer, IL-6 has been shown to promote tumor stem cell self-renewal and epithelial-to-mesenchymal transition (EMT), thus facilitating breast cancer metastasis." (PMID 34001144, 2021). "With the release of IL-6 and nitric oxide, phosphorylation of STAT3 and activation of the NOTCH signaling pathway, the crosstalk effects between MDSCs and breast cancer cells are activated." (PMID 34202411, 2021). "Paclitaxel enhances IRE1 RNase activity that leads to the production of IL6, IL8, CXCL1, GM-CSF, and TGFβ2 in breast cancer cells contributing to the expansion of tumor-initiating cells." (PMID 34447383, 2021). "In breast cancer, incessant activation of STAT3 appears to be attributable to the upregulation of the pro-inflammatory cytokine IL-6 and S1PR1." (PMID 34820423, 2021). "Others propose that stromal-derived IL-6, IL-8 and TGF-β1 stimulate breast cancer cell escape from dormancy in vitro." (PMID 33809315, 2021). "The inflammatory cytokine IL-17A, for example, binds to breast cancer cells and activates oncogenic ERK and NF-κB pathways, and can bind to fibroblasts and activate NF-κB and STAT3 pathways leading to production of IL-6 and G-CSF." (PMID 34359821, 2021). "Pro-inflammatory cytokines (IL-1β, IL-6, and TNF-α) not only play a potential role in the initiation of breast cancer (Section 3.2.1), but also in the progression of breast cancer." (PMID 34944905, 2021). "In breast cancer, lnc-BM increased JAK2 kinase activity to mediate oncostatin M- and IL-6-triggered STAT3 phosphorylation, promote ICAM1 and CCL2 expression, and mediate macrophage recruitment to the brain and consequently metastasis." (PMID 34123857, 2021). "Among the pathways in cancer indicated by KEGG analysis, the upregulated miR-222 was involved in pivotal pathways, such as OSM, IL-6 and ERK/MAPK signaling pathways in breast cancer, known pathways to be activated in IBC." (PMID 33901254, 2021). "Verification by ELISA revealed that IL-6 was significantly upregulated in met-high TCM in both melanoma and breast cancer models." (PMID 34140316, 2021). "The breast cancer subnetwork is found to contain (i) valid biomarkers including PIK3CA, PTEN, BRCA1, AR and EGFR; (ii) validated drug targets TOP2A, CDK4, HDAC1, IL6, BRCA1, HSP90AA1 and AR; (iii) synergistic drug targets EGFR and BIRC5." (PMID 35053185, 2021). "In breast cancer, NKX6-1 increases IL-6 expression and promotes cell proliferation through an NKX6-1/IL-6 network." (PMID 33906647, 2021). "In the selected key specific DEGs for LumB-subtype breast cancer, the expression of CNTD2, NEURL, STAC2, AKR1C2, IL6, FREM1, and HOXA4 were significantly correlated with the prognostic survival of the patients." (PMID 33644115, 2021). "Here, we uncover its mechanistic significance by characterizing a novel resistin/LIN28A/Let-7a/IL-6/STAT3 signaling axis supporting the growth and stemness of breast cancer cells." (PMID 34572725, 2021). "A recent review described the mechanisms whereby chronic adipose tissue inflammation, with altered levels of adipokines and upregulation of cytokines (IL-1β, IL-6, and TNF-α), plays an important role in breast cancer prognosis." (PMID 34406210, 2021).
breast cancer (continued). "Voluntary wheel activity is also able to decrease IL-6 and TNF-α circulation in a chemically induced breast cancer model." (PMID 35008220, 2021). "These adipocyte secretory factors (IL-6, TNF-α and leptin) were identified in acquired breast cancer drug resistance." (PMID 34812105, 2021). "The secretion of IL6 is tightly regulated by autophagy, indicating that the autophagic activity in breast cancer cells and in cells from the tumor microenvironment, consisting of adipocytes or immune cells, regulates EMT via IL6/STAT and IL6 MAPK signaling." (PMID 34207792, 2021). "In other experimental conditions, PGJ2 reduced the expression of MMP-9 and breast cancer MCF-7 cell invasiveness, IL-6 production and neutrophil recruitment in gout arthritis, and mast cell infiltration in atopic dermatitis." (PMID 34764817, 2021). "The stromal cell derived leptin is reported to support cancer metastasis in estrogen receptor positive and triple negative breast cancer cells by enhancing EMT via upregulating SERPINE 1, IL-6, MMP-2, SNAI 2, TWIST 1, vimentin and downregulating E-cadherin." (PMID 34588926, 2021). "This study demonstrates that oestrogen deprivation increases breast cancer secretion of TNF, CCL5, IL-6, IL-8, and CCL22 and alters total human peripheral blood mononuclear cell migration in an in vitro assay." (PMID 34602068, 2021). "Other studies have also highlighted the relationship between impaired IL-6 signalling and a heightened relapse rate, identifying baseline T cell response to IL-6 as a predictor of RFS in breast cancer." (PMID 33804027, 2021). "To further demonstrate the critical role of the proinflammatory cytokine secretion by breast cancer cells in SMAD3‐mediated tumor metastasis, we generated IL‐6 KO 4T1 cells and found that IL‐6 KO inhibited SMAD3‐2KQ‐induced MDSCs recruitment." (PMID 34392614, 2021). "IL6 and IL8, present in the SASP, favor the acquisition of migration/invasion and stem-like features, increasing tumor aggressiveness in breast cancer cells." (PMID 34447383, 2021). "Breast cancer, for example, is characterized by an elevated secretion of proinflammatory cytokines (IL-1, TNF-α, IL-6) or anti-inflammatory cytokines (IL-10), chemokines and chemokine receptors (CXCL8, CXCR4), and angiogenic factors (VEGF)." (PMID 35111484, 2021). "Our study has elucidated the molecular mechanism through which BQ can modulate the expression of IL-6 and IL-6R and thus the activation of STAT3 in breast cancer." (PMID 33806019, 2021). "A manifold of cytokines including IL-2, IL-6, IL-8 or IFN-γ have been described to be secreted by breast cancer cells." (PMID 33538861, 2021). "A clinical trial has demonstrated that San Huang decoction remarkably reduced the volume of exudate after breast cancer surgery and the expression of TNF-α, IL-6, IL-8 and C-reactive protein (CRP) to improve the inflammation." (PMID 34722304, 2021). "Thus, as well as having a direct role in suppressing cancer growth, as evidenced by studies with oestrogen-receptor-positive breast cancer cells, IL-6 released from skeletal muscle during exercise may also play an indirect role through the induction of an anti-inflammatory environment." (PMID 33864493, 2021). "Here, IL6 and HOXA4 were found to be specifically downregulated, and their low expression predicted low RFS in LumB-subtype breast cancer (p < 0.05), and the prognostic analysis result of IL6 was consistent with tha in all breast cancer." (PMID 33644115, 2021). "In breast cancer, CAFs secrete a variety of cytokines, including CXCL10, IL6, and IL8, which promote glycogenolysis and inhibit glycogen synthesis in breast cancer cells, ultimately leading to an increase in glycolysis." (PMID 34540683, 2021). "This study identifies the molecular mechanisms through which BQ323636.1 can enhance IL-6 and IL-6R expression, which leads to the activation of STAT3 and the development of tamoxifen resistance in ER+ breast cancer." (PMID 33806019, 2021).
breast cancer (continued). "It is now thought that tumor-derived factors (TDFs) IL-6, VEGF, and G-CSF secreted by tumor itself in TME of breast cancer have the ability to stimulate STAT3 cascade in myeloid cells differentiation." (PMID 33957948, 2021). "Interleukin-6 (IL-6) and IFN-γ activate STAT3 and STAT1 proteins, which bind to the MUC1 promoter region to enhance gene transcription in breast cancer cells." (PMID 34681277, 2021). "A pro-migratory role for GPER in breast CAFs was demonstrated as a result of the hypoxia-driven expression of VEGF, interleukin-6 (IL-6), and CTGF, with enhanced invasion of breast cancer cells occurring in a GPER/CTGF-dependent manner." (PMID 33802978, 2021). "Oncostatin M (OSM), a cytokine and a member of the IL-6 family, can upregulate and phosphorylate IL-6 and STAT3, respectively, advancing breast cancer progression." (PMID 34488773, 2021). "Resistin also enhanced IL6-driven STAT3 phosphorylation promoting growth and invasion of breast cancer cells." (PMID 34071280, 2021). "In breast cancer cell lines MDA-MB-468 and MCF-7, the IL-6/STA3 pathway plays a crucial role in EMT by upregulating TGF-β, a multifactorial cytokine that is again a target of RFX1 and a downstream signaling molecule of CD44 in breast cancer cells." (PMID 33964962, 2021). "The IL-6/STAT3 signaling cascade modulates PIM1, a proto-oncogene that induces cell invasion and upregulates the expression of EMT in breast cancer." (PMID 34488773, 2021). "Studies have shown that the pathogenesis of breast cancer is closely related to a significant increase in the expression levels of inflammatory factors such as TNF-α and IL-6 in TNBC." (PMID 34838003, 2021). "It was reported that the activation of NF-κB and the IL-6/STAT3 pathway can promote EMT in a variety of cancers and that blocking NF-κB reduces metastasis in breast cancer." (PMID 33855091, 2021). "Previously, IL-1β-mediated induction of IL-6 has been shown in numerous cell types, including MCF7 human breast carcinoma cells, human mast cells, fibroblasts, endothelial cells, keratinocytes, and peripheral blood monocytes." (PMID 34831450, 2021). "The treatment induced a metabolic switch in fibroblasts (a so-called catabolic tumor stroma phenotype) with increased secretion of interleukin-6 (IL-6) in co-cultures and resulted in activating stemness-related signaling (Hedgehog /GLI) in breast cancer cells." (PMID 32824649, 2020). "IL-6 is a strong stimulator of STAT3 pathway which is important in regulating survival and growth of breast cancer cells." (PMID 32649314, 2020). "In the breast cancer cell lines T47D and MCF-7, the stimulation with IL-6 induces the expression of PIM1 and the expression of EMT and stemness markers." (PMID 32478091, 2020). "Adipokines (leptin, adiponectin, autotaxin, interleukin 6, TNFα, and HGF) secreted by adipocytes increase the mitochondrial β-oxidation in breast cancer cells." (PMID 32015297, 2020). "The IL‐6/JAK/STAT3 pathway modulates the expressions of several genes involved in the proliferation, survival, and transformation of breast cancer cells." (PMID 33133558, 2020). "Polarization of macrophages towards the cancer-promoting M2 phase is stimulated by tumor cell-derived sEVs: breast cancer-derived sEVs induce M2 polarization of macrophage via glycoprotein 130/STAT3 signaling, resulting in IL6 secretion." (PMID 32015297, 2020). "Stimulation of the β-ARs increased the production of IL-6 in MDA-MB-231 and MDA-MB-231BR breast cancer cell lines and VEGF production in MDA-MB-231BR cells." (PMID 32092997, 2020). "Pathogenic polymorphisms of other inflammatory genes like NRF2, IL1α, IL1β, IL6, IL8, and CXCR2 have also been identified in Tunisian and Egyptian breast cancer patients." (PMID 33659210, 2020). "Resistin promotes the growth and aggressiveness of breast cancer cells through STAT3 activation, indicating a potential role of resistin, IL-6 and STAT3 in breast cancer racial disparity in AA women." (PMID 32824813, 2020).
breast cancer (continued). "The Health Aging and Body Composition study of women aged 70–79 years old evaluated baseline inflammatory markers (e.g., IL6, TNFRα, CRP) and incident breast cancer events." (PMID 33004039, 2020). "When preadipocytes were cocultured with breast cancer cells, there was enhanced CAF marker expression and IL-6 secretion, which promotes tumourigenesis; although the activation of Notch was not investigated." (PMID 32575680, 2020). "Our results showed that it decreased the release of pro-inflammatory and pro-angiogenic cytokines (IL-6 and IL-8) and MMP-9, which are regarded as factors for breast cancer cell invasion and stimulation of angiogenesis." (PMID 33260615, 2020). "For example, breast cancer cells are shown to respond to higher circulating levels of certain pro-inflammatory cytokines, such as TNF-α, IL-1β, and IL-6 by increasing the expression of P450 aromatase." (PMID 32731638, 2020). "CEBPD promotes the proliferation of breast cancer stem cells by activating IL‐6 and HIF‐1 in breast cancer." (PMID 32997416, 2020). "Specifically, the inflammatory cytokine interleukin-6 (IL-6) has been shown to induce CYP1B1 via miR27b in colorectal and breast cancer cells." (PMID 33185690, 2020). "Adipose stroma cell-derived IL-6, oncostatin M (OSM), and C-C motif chemokine ligand 2 (CCL2) have been shown to promote breast cancer cell proliferation, migration and invasion." (PMID 32242230, 2020). "Moderate exercise can reduce the expression of mRNA levels of TNF-α, IL-6, IL-18, and CRP in the livers of breast cancer mice." (PMID 32309219, 2020). "The upregulation of IL-6/STAT3/ROS can lead to the transcription of genes involved in breast cancer progression, as well as an augmentation in inflammation and generation of breast cancer stem cells (BCSCs)." (PMID 33138097, 2020). "While there has not been a comprehensive comparison of the downstream pathways activated by each ligand in breast cancer, many mechanistic studies have identified STAT3 as the key downstream mediator of IL-6 and OSM tumor-promoting effects." (PMID 32023849, 2020). "The secretion of IL-6 is an important factor for CSC conservation as well as maintenance, and promotes the CD44+/CD24 low phenotype in breast cancer." (PMID 32391363, 2020). "After the colonization of DTCs, bone-derived TGF-β stimulates breast cancer cells to synthesize PTHrP, prostaglandin E2 (PGE2), IL-1, IL-6, and IL-11." (PMID 32117996, 2020). "IL-6, IL-8, and MMP-9 belong to the group of factors that participate in breast cancer cell invasion and adhesion." (PMID 33260615, 2020). "Studies have shown that high expression levels of IL-6 and TNF-α in breast cancer can lead to a decrease in survival and a significant increase in mortality, which is beneficial to the progression and dissemination of breast cancer." (PMID 32936241, 2020). "Mechanistically, the overexpression of COX-2 in TAMs activates the AKT pathway in breast cancer cells by releasing IL-6 and PGE2, thereby inducing the expression of MMP-9 and promoting EMT in breast cancer cells." (PMID 33224886, 2020). "Oncogenic pathways such as IL-6/Stat3, EGFR, NOTCH and TGF-β1 are involved in breast cancer (BC) cell mesenchymal phenotype and stemness." (PMID 32894152, 2020). "The mature adipocytes facilitate the invasive behavior of breast cancer cells and trigger an EMT-phenotype via paracrine IL-6/STAT3 signaling." (PMID 33123472, 2020). "In this study, the presence of EBV and HPV in breast cancer significantly increased expression of the pro-carcinogenic factors, TGF-β and IL-6 (and IL-6-related IL-11) in breast tissue compared with viral-negative tissue." (PMID 32458652, 2020). "Mindful based stress reduction positively influences cytokine production (IL-6 and TNF-alpha) in breast cancer patients." (PMID 32434503, 2020). "We selected a set of five inflammatory factors (IL1A, IL6, IL17A, IFNβ, and NFĸB) that were found to be overexpressed in aggressive breast carcinomas." (PMID 33396463, 2020).
breast cancer (continued). "Triggering of the TLR2/MyD88 signaling pathway by TEV derived from thymoma, mammary carcinoma or colon carcinoma cells and containing HSP72, has been shown to induce IL-6 production by MDSC and autocrine activation of STAT3." (PMID 32878277, 2020). "CAFs isolated from human breast cancer secrete abundant levels of PGE-2, which enhances the secretion of IL-6 to expand CSCs." (PMID 31417869, 2019). "Our results in this study also showed that IL-6 induced MMP2 and MMP9 expression in breast cancer cell and mediated cell migration." (PMID 31409371, 2019). "We have previously reported human adipocytes induce EMT in MDA-MB-468 and MCF-7 breast cancer cells through paracrine IL-6 activation of STAT3, enhancing breast cancer cell migration and invasion, by induction of EMT19." (PMID 31383893, 2019). "We have shown that in breast cancer cells specifically IBC, silencing of Sdc-1 drives downregulation of IL-6 and its signaling pathway components." (PMID 31145753, 2019). "We also proved that ERα-36 was also associated with STAT3 and influenced phospholyation and acetylation of STAT3, which was required for IL-6-induced MMP2 and MMP9 expression and breast cancer cell migration." (PMID 31409371, 2019). "IL-6 induces the expression of RANK by breast cancer cells, which sensitizes the tumor to RANKL and enhances cancer IL-6 release." (PMID 31847214, 2019). "We next examined the effect of MTF on the activation of IL-6-induced STAT3 and NF-κB in MBCDF and MBCD17 primary breast cancer cells." (PMID 31337349, 2019). "In breast cancer cells, IL-6 expression activates STAT3 which subsequently upregulate the expression of IL-6 creating an IL-6/STAT3 autocrine loop allowing for continual activation of the axis to drive tumour growth." (PMID 31383893, 2019). "In this study, co-culture of conditioned macrophages and breast cancer cells resulted in strong, sustained increase of TNF-α and IL-6 protein levels." (PMID 30736340, 2019). "We have recently demonstrated that MH affects multiple functions of breast cancer cells through the inhibition of p-STAT3 functional activity and IL-6 secretion." (PMID 31491838, 2019). "Inflammatory factors (CCL5, IL-6, etc.)and transporters (MCT1, CD36, etc.)are potential targets for breast cancer treatment." (PMID 31500658, 2019). "However, IL-6-mediated STAT3 activation has frequently been suggested to be a protective mechanism in chemotherapy-induced cell death through the increased expression of anti-apoptotic proteins such as Bcl-2 or survivin in solid tumors such as breast cancer and prostate cancer." (PMID 30927911, 2019). "Further, our identification of increased IL8, IL6, HAS2, and ICAM1, as well as decreased ERBB2 in MpBC samples matches findings from a microarray comparison of gene expression between metaplastic breast cancers and ductal carcinomas of the breast." (PMID 31488082, 2019). "Several investigations also emphasized IL6, IL8, CCL2, and CCL5 as stimulators of the survival, proliferation, and invasion of breast cancer cells." (PMID 31398937, 2019). "A recent study showed that serum IL-6, IL-8, and TNF-α were positively correlated with clinical tumor stage and lymph node status in Chinese breast cancer patients." (PMID 31430979, 2019). "NOTCH activation through NO facilitates constitutive IL-6-dependent STAT3 activation, promoting breast cancer stemness." (PMID 30885232, 2019). "The expression levels of different inflammatory factors including IL-1, IL-6, IL-17, TGF-β, TNF-α, NF-κB, and RONS were statistically higher in HPV- positive breast cancer patients than control samples and HPV-negative breast cancer patients." (PMID 30642295, 2019). "It has been also shown that breast cancer-derived exosomes are enriched with gp130, which induces gp130/STATS signaling in macrophage and leads to the secretion of IL-6 for macrophage polarization." (PMID 31686989, 2019).